GTF3C6 (general transcription factor IIIC subunit 6)
Description:
Involved in RNA polymerase III-mediated transcription. Integral, tightly associated component of the DNA-binding TFIIIC2 subcomplex that directly binds tRNA and virus-associated RNA promoters.
Synonyms: TFIIIC35; C6orf51; bA397G5.3
Tractability: PROTAC: ubiquitination databases record sites on it.
Gene: Protein-coding gene on chromosome 6 (110,958,477 to 110,968,586, forward strand). Ensembl gene ENSG00000155115.
Subcellular location: Nucleus
Subcellular location (Human Protein Atlas): Nucleoplasm; Nuclear bodies
Pathways (Reactome):
Gene expression (Transcription): RNA Polymerase III Abortive And Retractive Initiation; RNA Polymerase III Transcription Initiation From Type 1 Promoter; RNA Polymerase III Transcription Initiation From Type 2 Promoter
Gene Ontology:
Molecular function: DNA binding; protein binding; RNA polymerase III general transcription initiation factor activity
Biological process: transcription by RNA polymerase III; transcription initiation at RNA polymerase III promoter; 5S class rRNA transcription by RNA polymerase III; tRNA transcription by RNA polymerase III
Cellular component: nuclear body; nucleoplasm; nucleus; transcription factor TFIIIC complex
Genetic constraint (gnomAD): Loss-of-function variants: 10 observed, 12.34 expected, observed/expected ratio (o/e) 0.81, 90% interval 0.5 to 1.37. The upper end of that interval is the gene's LOEUF score, 1.37, which puts it in group 5 of 6, group 1 being the genes least tolerant of losing a copy. Missense variants: 166 observed, 185.42 expected, observed/expected ratio (o/e) 0.9, 90% interval 0.79 to 1.02. Synonymous variants: 62 observed, 60.03 expected, observed/expected ratio (o/e) 1.03, 90% interval 0.84 to 1.28.
Homologues: Orthologues: chimpanzee GTF3C6 (97% identical), macaque GTF3C6 (96% identical), pig GTF3C6 (82% identical), dog GTF3C6 (82% identical), mouse Gtf3c6 (72% identical), rat Gtf3c6 (71% identical), tropical clawed frog gtf3c6 (51% identical), zebrafish gtf3c6 (31% identical), Drosophila melanogaster CG42516 (15% identical).
Diseases named in the same sentence as GTF3C6 in open-access papers:
GTF3C6 is named in the same sentence as 2 diseases in open-access papers, as found by Europe PMC text mining. Sharing a sentence is not in itself a finding about the gene and the disease. The quoted sentences say what the papers report.
hepatocellular carcinoma (2 papers, 2021 to 2025). A malignant tumor that arises from hepatocytes. "Researchers have indicated that a 15-characteristic gene, including GTF3C6, may affect the prognosis of hepatocellular carcinoma." (PMID 41262242, 2025).
GTF3C6 also shares sentences with these, for which no sentence is quoted: cancer (1 paper).